Y_RNA (Y RNA )
Gene: Miscellaneous RNA gene on chromosome 8 (100,185,138 to 100,185,239, forward strand). Ensembl gene ENSG00000199667.
Homologues: Orthologues: chimpanzee Y_RNA (100% identical), guinea pig Y_RNA (95% identical), macaque Y_RNA (93% identical). Paralogues in human: RNY3 (95% identical), Y_RNA (95% identical), RNY3P1 (94% identical), Y_RNA (94% identical), Y_RNA (93% identical), Y_RNA (92% identical), Y_RNA (91% identical), Y_RNA (90% identical), RNY3P11 (89% identical), Y_RNA (89% identical), RNY3P14 (88% identical), RNY3P5 (88% identical), and 101 more.